PPARA (peroxisome proliferator activated receptor alpha)
Diseases named in the same sentence as PPARA in open-access papers (continued):
Sharing a sentence is not in itself a finding about the gene and the disease.
Obesity (continued). "Based on the results, regarding the mechanism of SZ-A reducing obesity in adipose tissue, it can be concluded that SZ-A could promote triglyceride catabolism and oxidation by up-regulating the expression of PPARα, ATGL, and p-HSL and promoting p-ACC to reduce fatty acid synthesis." (PMID 36501080, 2022). "However, the protective effect of PPARα against obesity and NAFLD has been demonstrated in both human and animal studies, effects that were attributed to their hypolipidemic, hypoglycemic, and anti-inflammatory effects, as well as their ability to improve insulin sensitivity." (PMID 36615764, 2022). "Besides these, recently, lots of experiments related to obesity in whole-body PPARα− deficient mice (PPARα−/−) and in mice lacking PPARα only in hepatocytes (PPARαhep−/−) were performed." (PMID 35163881, 2022). "According to these data, higher expressions of SLC27A2, FASN, PPARα, and INSR genes in the children’s blood reflected a protective role of breastfeeding, as these genes are indicators of a lower risk of developing insulin resistance and dyslipidemia linked with obesity in children." (PMID 34073649, 2021). "Therefore, the reduced serum levels of adiponectin in people with obesity and T2D may contribute to the observed impairment in PPARα activity." (PMID 32708786, 2020). "Furthermore, melatonin may alleviate insulin resistance and obesity by activating the AMPKα/PPARα signaling pathway." (PMID 33150187, 2020). "Additionally, however, utilizing tesaglitazar provided an opportunity to test whether delivery of a PPARα/γ dual agonist to macrophages was sufficient to improve metabolic outcomes in a murine model of obesity." (PMID 31903139, 2020). "In particular, PPARα and PPARβ/δ play a central role in the oxidation of fatty acids, as well as in the improvement of lipid and cholesterol profiles, which reduces adiposity and prevents the development of obesity, while PPARγ contributes to energy storage by enhancing adipogenesis." (PMID 32630591, 2020). "PPARα may also potentially be a key mediator of the increased reliance on TAG-derived fatty acid oxidation in obesity/T2D, as 13C nuclear magnetic resonance spectroscopy studies revealed increased TAG turnover in cardiac-specific PPARα overexpressing male mice fed a high-fat diet for 2 weeks." (PMID 33041869, 2020). "However, most past studies have failed to unravel the underlying mechanisms with the exception of one study, in which RAP1 protected mice from obesity by promoting the transcription of Pparα and Pgc1α by directly binding to the upstream regulatory regions of these genes." (PMID 30796637, 2019). "Thus, KLF15/PPARα may interact with Sirt3 to regulate Sirt3 activity or expression in response to obesity and thus regulate ACADVL acetylation." (PMID 30061171, 2018). "This suggests that the observed increase in vanin-1 expression in steatotic livers of obese mice, may rather be a marker of enhanced PPARα activation, without causal involvement of vanin-1 in the progression or prevention of steatosis during obesity." (PMID 26932716, 2016). "Interestingly, PPARα null mice, which are unable to properly upregulate gluconeogenesis and ketogenesis in response to a fast, are protected from metabolic responses (hyperglycemia and hyperketonemia) common to obesity induced lipid accumulation." (PMID 27708682, 2016). "New generation drugs - PPARα/γ dual agonists - reveal hypolipemic, hypotensive, antiatherogenic, anti-inflammatory and anticoagulant action while the overexpression of PPARβ/δ prevents the development of obesity and reduces lipid accumulation in cardiac cells, even during a high-fat diet." (PMID 24524207, 2014). "Therefore, the use of pomegranate-derived compounds and fatty acids holds promise as prophylactic interventions for obesity and diabetes since some of them are PPARα and PPARγ activators that contribute to correct the abnormalities of lipid metabolism and regulate inflammatory responses." (PMID 23737845, 2013).
Obesity (continued). "Fibroblast growth factor 21 (FGF21), whose expression is induced by peroxisome proliferator-activated receptor α (PPARα), has been recently identified as a novel metabolic regulator which plays a crucial role in glucose homeostasis, lipid metabolism, insulin sensitivity and obesity." (PMID 22394566, 2012). "Since these two mediators are dysregulated in several tissues of obese Zucker rats, these data might suggest that KO can potentially produce beneficial metabolic effects against dysmetabolism and inflammation in obesity also by re-equilibrating the activity of PPARα." (PMID 21749725, 2011). "In female ovariectomized mice, 17β-estradiol inhibits the actions of fenofibrate on obesity through its suppressive effects on the expression of PPARα target genes, and these processes may be mediated by inhibiting the coactivator recruitment of PPARα." (PMID 20871824, 2010). "Thus, fenofibrate influences obesity via the differential activation of PPARα." (PMID 20871824, 2010). "Moreover, PPARα agonist treatment has been reported to improve pancreatic β-cell function in insulin-resistant rodents and the adaptive response of the pancreatic β-cell function to pathological conditions, such as obesity." (PMID 20871824, 2010). "Although E2 alone decreases body weight gain and WAT mass, E2 may impair PPARα actions on obesity." (PMID 20871824, 2010). "Thus, pancreatic PPARα signaling appears to besignificant “in vivo” and, when PPARα is activated due toelevated fatty acid levels, as in obesity, it may contribute toglucose intolerance and β-cell dysfunction." (PMID 17389766, 2007). "The human data shows that obesity enhances the activation of the FA/HIF‐1α/CCL2 pathway in tumor tissue and the CCL2/CCR2/PPARα axis in adjacent adipose tissue, thereby accelerating tumor progression and promoting adipolysis in the surrounding adipose tissue." (PMID 41160815, 2026). "Taken together, our findings indicate that in breast cancer patients, obesity enhances the activation of the FA/HIF‐1α/CCL2 axis in tumor tissues and the CCL2/CCR2/PPARα axis in adjacent adipose tissue." (PMID 41160815, 2026). "Disruptions in PPARα signaling or microbiome function can impair this balance, contributing to MASLD, obesity, and related metabolic disorders." (PMID 40926269, 2025). "Altogether, our results reveal a key role for PPARα in DNL in BAT and in the regulation of lipid metabolism in HFD-induced obesity." (PMID 40499650, 2025). "The pharmacological modulation of PPARα, CB1, or GLP-1 receptor activity has demonstrated beneficial effects, including anti-obesity actions." (PMID 40141063, 2025). "This may also be driven by PPARα, as studies by Nakamura and colleagues have demonstrated that a specific PPARα transcriptional signature regulated by glycogen synthase kinase 3α (GSK3α) contributes to cardiac lipid accumulation and lipotoxicity in obesity/T2D." (PMID 40663803, 2025). "Recent studies have identified an intestinal PPARα-fatty acid-binding protein 1 (FABP1) axis that regulates dietary fatty acid uptake and influences obesity and MASLD progression." (PMID 41438090, 2025). "Studies have shown that FXR agonists confer renal protection in obesity-related CKD by downregulating SREBP-1 and upregulating PPARα, CPT1a, and PGC-1α." (PMID 39765868, 2024). "Previous studies have indicated that fatty acid oxidation and the activity of enzymes involved in mitochondrial fatty acid transport and oxidation, such as CPT-1α, PPARα, and CD36, are lower in skeletal muscle during obesity and insulin resistance." (PMID 39596482, 2024). "Taken together, our molecular dynamics results suggest that OA has binding stability to core targets, especially PPARG, PPARA, and PTGS2, which have very high potential in OA anti-obesity." (PMID 38246999, 2024). "The activation of PPARα optimizes the TCA cycle’s function, offering a strategy for improving metabolic health and addressing conditions like obesity." (PMID 39590839, 2024).
Obesity (continued). "On the other hand, after receiving 100 or 150 mg/kg of 7-MEGATM, the levels of PPARα and UCP-1 increased in HFD groups, suggesting that lipid metabolism had improved in HFD mice thereby ameliorating obesity." (PMID 38909257, 2024). "The deletion of NCoR1 in IECs activated PPARα and LXR, and together, these two signaling pathways changed the energy balance to reduce anabolism and increase catabolism, thereby alleviating obesity and metabolic syndrome." (PMID 39807334, 2024). "For example, administration of SCFAs can decrease the lipid accumulation in the liver of animal models of obesity and T2DM, via increasing hepatic AMPK phosphorylation and expression of PPARα, and further stimulating FFA oxidation." (PMID 36698477, 2022). "Berberine blocks food absorption, reduces body gain, and visceral adipose weight by decreasing the level of PPARγ in high-fat diet-induced obesity mice when the level of GATA-binding proteins 3 increases and downregulates the expression of PPARγ and PPARα." (PMID 36263142, 2022). "These miRNAs were suspected to target the molecules including STAT3, PI3K, AKT and FOXO1 in leptin signal in obesity, PPARγ and FOXO1 in adipogenesis pathway, and p38MAPK, PPARγ and PPARα in white adipose tissue browning pathway." (PMID 36065413, 2022). "In this paper, we set out to study the impact of PFOA and GenX in a mouse model of diet-induced obesity, glucose intolerance, and NAFLD, and investigate the role of PPARα in mediating the metabolic effects of PFOA and GenX." (PMID 36115532, 2022). "Studies indicated that PPARα activated UCP1 and promoted the expressions of the genes related to thermogenesis to repress HFD-induced obesity." (PMID 34174964, 2021). "Our study discovers a new key function for the TBX15 TF in trans regulating an adipose co-expression network of 347 adipose, mitochondrial, and metabolically important genes, including PPARG, KLF15, PPARA, ADIPOQ, and 35 obesity GWAS genes." (PMID 34340684, 2021). "Our study discovers a novel key function for the TBX15 TF in trans regulating an adipose co-expression network of 347 adipose, mitochondrial, and metabolically important genes, including PPARG, KLF15, PPARA, ADIPOQ, and 35 obesity GWAS genes." (PMID 34340684, 2021). "Along these lines, the SREBP antagonist, agonist of PPARα, GLP-1RA, SGLT-2 blockers and ongoing clinical trials focusing on dietary intervention hold promise for the treatment of obesity mediated nephropathy." (PMID 34268323, 2021). "All of these actions of PPARα in the WAT can enhance energy consumption and improve adipocyte hypertrophy, as well as obesity-induced insulin resistance." (PMID 34445679, 2021). "Taken together, our data demonstrate that hepatocyte-specific deletion of Pparα promotes steatosis and inflammation in HFD-induced obesity and provide further pre-clinical evidence that hepatocyte PPARα is a relevant direct target in NAFLD." (PMID 32300166, 2020). "This suggests that the hepato-specific and whole-body deletions of Pparα have distinct and specific consequences in the hepatic response to HFD-induced obesity." (PMID 32300166, 2020). "In fact, transgenic mice that express in adipose tissues constitutive active human PPARα, presented under HFD, recovered insulin sensitivity, suggesting an important role of this NR in attenuating obesity-induced insulin resistance in WAT." (PMID 31683535, 2019). "Several of these genes, like LEP, PPARA, PPARD, LPIN1, SREBP1, and ADIPOQ are described in obesity in both humans and mice." (PMID 31921306, 2019). "On the other hand, it was demonstrated that PPARα and its target genes, including CPT-1, were significantly decreased in HFD-induced obesity." (PMID 30558262, 2018). "In our previous study, we also showed that the downregulation of CPT2 in obesity- and NASH-driven HCC was, at least in part, attributed to decreased peroxisome proliferator-activated receptor alpha (PPARα)." (PMID 30445800, 2018).
Obesity (continued). "It is reported that PPARα/PGC-1 signaling pathway can be activated by chronic overnutrition and obesity, resulting in the up regulation of fatty acid β-oxidation related genes, such as FATP1, FACS1, UCP2 and UCP335." (PMID 26150313, 2015). "SIRT1 deletion in hepatocytes impaired the activity of PPARα, resulting in development of hepatic steatosis, whereas SIRT1 hepatic overexpression suppressed the expression of gluconeogenic genes and attenuated obesity-induced ERS." (PMID 26539534, 2015). "Hepatic mRNA expression of circadian (CLOCK, BMAL1, REV-ERBα, CRY, PER) and metabolic (PPARα, SIRT1) genes were strongly suppressed in offspring exposed to both maternal obesity and HFD." (PMID 24416203, 2014). "Collectively, our results indicated that the combination of maternal obesity and HFD led to the greatest disruption of core clock machinery and reductions of PPARα mRNA expression." (PMID 24416203, 2014). "For example, administration of both, PPARα agonists such as fibrates and FGF21 lowered LDL-cholesterol, raised HDL-cholesterol, improved insulin sensitivity and prevented diet-induced obesity in rhesus monkeys and rodents." (PMID 22394566, 2012). "Activation and elevation of PPARα and PPARδ expression is known to increase expression of CPT1, ACO and UCP3 to elevate energy expenditure, subsequently resulting in anti-obesity actions." (PMID 21799697, 2011). "T2D, age, obesity- all increases ROS that in turn increases lipid oxidation, via ROS/FOXO/PPARG/PPARA/β-catenin regulation leads to PPARG activation and repression of Wnt-signaling." (PMID 20942928, 2010). "Interestingly, there are data indicating that PPAR/RXR heterodimers are capable of binding to estrogen response elements (EREs), and PPAR and estrogen receptors (ERs) share cofactors, suggesting that signal cross-talk may exist between PPARα and ERs in the control of obesity." (PMID 20871824, 2010). "Thus, PPARα may be involved in energy balance and obesity by regulating UCPs." (PMID 20871824, 2010). "Overall, fenofibrate treatment affects body weight, adipose tissue mass, lipid metabolism, and hepatic β-oxidation with sexual dimorphism, but fenofibrate-regulated obesity is not directly associated with PPARα-mediated action and may be influenced by sex-related factors." (PMID 20871824, 2010). "It is noteworthy that the functional importance of SREBP1, PPARα/γ, NR3H1 and LEP in obesity has been shown in many genetic studies." (PMID 20961460, 2010). "This study revealed that SREBP1, PPARα/γ, NR3H1 and LEP are key regulatory factors in these pathways and are expressed in zebrafish and mammalian obesity." (PMID 20961460, 2010). "In combination with PPARα activation, better improvement was achieved for obesity, insulin resistance, and hepatic steatosis, independent of FGF21 induction." (PMID 40815899, 2025). "Although our current work highlights the potential role of FAO induction by PPARα in ameliorating obesity‐driven chemoresistance, it does not preclude the involvement of other PPARα‐dependent pathways." (PMID 38145969, 2024). "Among the most frequently observed genes in metabolism-related processes, examples include AhR and LXR in AOPs associated with steatosis (e.g., AOP IDs 34, 57, 58 and 232), PPARα in AOPs describing lipid metabolism alterations (e.g., AOP ID 166), and ERα in an AOP related to obesity (AOP ID 493)." (PMID 38523647, 2024). "Moreover, ellagic acid can impact anti-obesity by upregulating the rate at which brown adipocytes express PGC-1α and PPARα." (PMID 38111312, 2024). "Moreover, OEA, a fatty acid ethanolamine, is an endogenous peroxisome proliferator-activated receptor-alpha (PPAR-α) agonist, and it is a lipid mediator that alleviates obesity and hyperlipidemia." (PMID 38983766, 2024). "This research aims to explore the anti-obesity potential of morin in rats subjected to a high-fat diet (HFD) and investigate whether its effects are mediated through PPARα regulation." (PMID 39202687, 2024).
Obesity (continued). "From our data, we found that PPARδ, rather than PPARα or PPARγ, plays an active role in the anti-obesity effect of BBR." (PMID 37511356, 2023). "Punicic acid ameliorates glucose tolerance and obesity-related inflammation in animal models of obesity and type 2 diabetes by acting as dual PPARα and γ agonists with no adverse side effects detected in toxicological studies." (PMID 36675252, 2023). "In addition, mTOR is also involved in the transcription factors SREBPs, PPARγ/PPARα and TFEB in lipid metabolism, which is related to the development of tumours, obesity, and fatty liver." (PMID 36611986, 2023). "Mice lacking PPARα develop liver steatosis during fasting and obesity with aging, and are protected from high fat diet-induced insulin resistance." (PMID 37181042, 2023). "Moreover, obesity was found to result in PPAR-driven lipid accumulation in NK cells, and the administration of FAs along with PPARα/δ agonists (i.e., mimicking obesity) blocked mTOR-regulated glycolysis." (PMID 37205182, 2023). "This study suggests that CPEF may exert its anti-obesity effects by promoting thermogenesis and fatty acid oxidation via inducing UCP1 and PPARα expression, and that hesperidin and neoponcirin may be responsible for these effects." (PMID 36835279, 2023). "In addition, several of the CYP2B6-produced 9- and 13-position oxylipins are PPARα and PPARγ activators, providing a putative mechanism for CYP2B6 as an anti-obesity enzyme." (PMID 36520866, 2022). "Using the integrated strategy of network pharmacology and greedy algorithms, the important roles of some targets IL6, HMCGR, PPARA, and APOB for management of hyperlipidemia and obesity were highlighted in this work, which was also in accord with the previous publications." (PMID 35586687, 2022). "On the other hand, the activation of PPARα reduces weight gain, whereas the inhibition of PPARγ decreases lipogenesis; unfortunately, current anti-obesity agents are not selective effectors for each subunit." (PMID 36501129, 2022). "Similar beneficial gut microbes have been shown to improve metabolic status in obesity and DM40, which may also involve PPARα signaling." (PMID 34188162, 2021). "Investigating the metabolic impact of the functional interaction of SIRT1 with SREBF1c and PPARα and insights into how NAD+ metabolism modulates adipocyte function could potentially lead to new avenues in developing therapeutics for obesity complications." (PMID 33854178, 2021). "Furthermore, a report demonstrated that the activator of PPARA, PPARD, and PPARG is of great anti-obesity therapeutics due to the regulation of fat and gluconeogenesis." (PMID 34889899, 2021). "In addition to obesity, other pathologies have shown to be impacted by mechanisms that involve CB1R and PPARα modulation." (PMID 33498245, 2021). "In ob/ob obese mice, the absence of PPARα resulted in increased obesity and led to severe hepatic steatosis." (PMID 34445672, 2021). "By enhancing the expression of fatty acid oxidation related factors in epididymal fat (PGC-1α, PPARα, and CPT-1a), activation of BAT and WAT browning, suggesting that MA treatment can improve obesity by regulating lipid metabolism and promoting energy expenditure." (PMID 33767670, 2021). "Taken together, these data suggest that TCN treatment regulates lipid metabolism via LKB1-AMPK signaling pathway and promotes β-oxidation by PPARα; hence, TCN may have potential remedy in the prevention and treatment of obesity." (PMID 33531919, 2021). "A previous report illustrated that DNA demethylation of Fgf21 gene induced by peroxisome proliferator activate receptor α (PPARα) during the postnatal period could increase hepatic FGF21 expression, which may partly attenuate diet-induced obesity in adulthood." (PMID 34349728, 2021).